CD44 (CD44 molecule (IN blood group))
Diseases named in the same sentence as CD44 in open-access papers (continued):
Sharing a sentence is not in itself a finding about the gene and the disease.
tumor (continued). "As expected, tumor-derived TGF-β1 established a systemic immunosuppressive environment that was represented by an increase of the CD4+Gr11b+ T-cell population and a decrease of the activated subpopulation of CD4+CD44+CD62L– T cells in lungs and spleens and CD8+IFNγ+ T cells in spleens." (PMID 27036297, 2016). "Furthermore, MFB was more effectively therapeutic in combination with docetaxel or cisplatin, and MFB, but not metformin, effectively targeted the CD44+/highCD24−/low population sorted from tumor cells prepared from mouse xenografts." (PMID 27223262, 2016). "The results obtained using CD44+/EpCAM+ double positive DU145 cancer stem cells concurred with the fact that bLf-Dox conjugates were more effective than Dox alone in reducing the aggressiveness of resistant cancer stem like cells by inhibiting their migration and tumour formation." (PMID 27576789, 2016). "Therefore, we performed a detailed expression analysis of the most frequently discussed putative markers of CSCs in PDAC (i.e., CD24, CD44, EpCAM, CD133, and nestin) in both human primary tumor samples and in the respective cell lines derived from those tumors." (PMID 27414409, 2016). "These HA/CD44-activated signaling regulators (PKCε, JNK, c-Src, Nanog, Stat-3, c-Jun, Oct4, Sox2 and Twist), together with various miRNAs could be used as structure/function-related tumor markers for human cancer detection and prognosis." (PMID 27070574, 2016). "As expected neither CD74 nor its co-receptor CD44 were detected in JL-1 tumor cells." (PMID 26883190, 2016). "Provided that CD44 is a bona fide GCSC marker and that FGFR2 is the most commonly deregulated RTK pathway in GC, CD44+/FGFR+ GC cells could be a key subset dictating tumor initiation, suggesting some coordination between these two molecules." (PMID 27107424, 2016). "Furthermore, inhibition of miR-125b or miR-20b induced MES-associated CD44 expression, but did not alter the levels of PN-associated SOX2 in these tumours." (PMID 27698350, 2016). "In addition, the secondary tumors resemble the phenotype (morphology and ESA/CD44/CD24 expression profile) of the initial tumor and the tumorigenic ESA+CD44+CD24− tumor cells could be serially passaged at least four passages in vivo." (PMID 26349457, 2016). "Here, we analyzed the expression of putative CSC markers—CD24, CD44, epithelial cell adhesion molecule (EpCAM), CD133, and nestin—by immunofluorescence, flow cytometry and quantitative PCR in 3 PDAC-derived cell lines and by immunohistochemistry in 3 corresponding tumor samples." (PMID 27414409, 2016). "In a reciprocal experiment, Dox-induced CD44 KD in vivo suppressed tumor growth in nude mice and in non-obese diabetic/severe combined immuno-deficient mice with IL2R knock-out (NOD/LtSz-scid/IL2Rγnull) (referred to here as NSG mice) purchased from Jackson Laboratory (Bar Harbor, ME) (NSG) mice." (PMID 27107424, 2016). "It is exciting to speculate that the CSC in MDBMSCC undergo EMT and preferentially express OCT4, pSTAT3, SOX2, and NANOG and potentially lose the expression of EMA and CD44, as none of these cells outside of the tumor nests express EMA or CD44." (PMID 27532037, 2016). "On the other hand, the expression of CD166, CD133, CD44, A2B5, CD56, NGFR and DCX seemed to be higher in UA cells, but also not statistically significant, while the expression of CD9, Nestin, GFAP, CD24, PDGFRb, PDGFRa, MAP2, TUBIII, S100 were consistently high in both UA and tumor core samples and." (PMID 27605047, 2016). "Additionally, no relevant changes in tumor proliferation [Ki67 immunohistochemistry (IHC)], CD44 expression (CD44 IHC), and CD44-mediated signaling (phosphorylated ERK IHC) was demonstrated in tumor tissue with RG7356 treatment (data not shown)." (PMID 27507056, 2016).
tumor (continued). "The ability of this treatment to target two mutually exclusive CD44-positive and CD44-negative cell populations, which appear to represent the bulk of tumor cells in GBM, may counteract some of the issues of intratumoral heterogeneity." (PMID 27906173, 2016). "Tumorigenic PC3 cells may be enriched by the ALDH+ phenotype but not ABCG2 whereas only the CD44+α2β1+ phenotype can enrich tumor-initiating cells in the LAPC4 model." (PMID 26246472, 2015). "By contrast, the spontaneous TRAMP mouse PCa model was used to illustrate that the trafficking of a naturally arising clonally expanded PCa histone H4-specific population of CD44+CD8+ T-cells to prostate tissue lessened tumor burden but failed to improve survival." (PMID 26217583, 2015). "To further investigate the absence of differences in tumor initiating potential (as determined by time to palpability) among the cells sorted for CD44/CD24, we analyzed whether any sub-population was enriched for ALDH." (PMID 26449187, 2015). "Only 50 cells of triple positive CD44+/ESA+/CD24+ cells could form a tumor whereas 1 × 104 CD44−/ESA−/CD24− cells could not." (PMID 25849939, 2015). "This dendrimer was able to downregulate CD44 mRNA and protein expression and inhibit tumor growth without toxicity, suggesting that the targeted delivery of CD44 siRNA along with chemotherapeutic agents may be explored for cancer therapy." (PMID 25954275, 2015). "In sharp contrast to the Du145 model, the CD44+α2β1+ LAPC9 cells were highly tumorigenic in that as few as 1 double-positive cell was able to regenerate a tumor and the regenerated tumor contained only a small % of CD44+α2β1+ LAPC9 cells and could be serially passaged (not shown)." (PMID 26246472, 2015). "Importantly, the tumor cell lung metastasis was inhibited in the mice injected with CD117+CD44+-shHOTAIR, whereas the metastatic tumor cells were found in the lungs of the mice injected with CD117+CD44+-scramble." (PMID 25792974, 2015). "Moreover, DHPMs modulate the CD44+/CD24− phenotype leading to a decrease in the CSC population in MDA-MB-231 cells, an important effect since CSC are resistant to many conventional cancer therapies and play a pivotal role in tumor initiation and maintenance." (PMID 25885813, 2015). "Despite these observations supporting the candidacy of CD133+CD44+α2β1hi cells as prospective PCSCs, it still remains to be demonstrated whether CD133+CD44+α2β1hi cells isolated from primary PCa tissues are capable of tumor initiation in vivo." (PMID 25595909, 2015). "However, a direct effect on tumor cells is possible as a result of the generation of low-molecular weight (LMW)-HA fragments that can compete with high-molecular weight (HMW)-HA for binding and activation of HABPs, including the HA receptors, CD44 and RHAMM." (PMID 26380222, 2015). "Finally, using systemic administration of anti-CD44 antibodies in vivo, we demonstrated that CD44 is an efficient therapeutic target for treating tumor relapse, but not primary PDAC tumors." (PMID 25797268, 2015). "This review describes the roles of HA interactions with CD44 and RHAMM in inflammatory responses and tumor development/progression, and how therapeutic strategies that block these key inflammatory/tumorigenic processes may be developed in rodent and human diseases." (PMID 25999946, 2015). "In conclusion, we described a paradigm in which through CD44, the signaling network consisting of AKT, ERK and Hippo-YAP pathways controls the expression of downstream genes that mediate contact inhibition, proliferation, cell cycle progression and maintenance of tumor initiating cells." (PMID 25605020, 2015).
tumor (continued). "CD44 and CD54 expressions were also found more frequently in early recurrence patients than those of late recurrence (P = 0.001, P = 0.037), suggesting that stem cell markers could be taken as a promoter for tumor progress." (PMID 25441488, 2014). "As a majority of studies have not taken into consideration that such CD44 analyses will detect a collection of isoforms, it is not surprising that no consensus opinion has been reached on the role of CD44 and its isoforms in tumor progression and cancer stem cells." (PMID 24122205, 2014). "Since xenograft tumors generated from both CD24+/CD44+ and CD24-/CD44+ cells showed the similar immunohistochemical staining, we hypothesized that the CD24+/CD44+ cells may have been generated during the in vivo tumor growth from CD24-/CD44+ cell subpopulation." (PMID 24612587, 2014). "ALDH1 enzyme activity defines a subpopulation of tumor cells which exhibit stem cell-like properties and whose prevalence correlates with survival in PC Additionally, a number of cell surface markers are co-expressed with ALDH1, such as CD44, CD24, CD133, and CXCR4." (PMID 24652403, 2014). "In the present study, we could not obtain consistent results that CD44-positive gastric tumor cells were tumorigenic by analyzing patient-derived tumor xenograft (PDTX) cells." (PMID 24015244, 2013). "Taking into consideration that CD44 is a transcriptional target of Notch-1, apparently downstream of Hes1/Hey1, we concluded that β-elemene could attenuate tumor angiogenesis by targeting GCSCs at least in part through Notch-1 expression." (PMID 23710217, 2013). "Decreased expression of CD44 and SOX2 might reduce the oncogenic potential of the tumor cells." (PMID 24156782, 2013). "Notably, DT-22 tumours generated in vivo from the CD24 negative population were found to contain rare CD44+CD24low+ cells (<4%)." (PMID 23982961, 2013). "The single Rb and CD44 knockdowns did not significantly alter primary tumor weight." (PMID 24324613, 2013). "By selectively eliminating CD44+ stem-like cells, it may be possible to treat patients with aggressive, non-resectable GCs, as well as preventing the tumours from metastasizing." (PMID 23833643, 2013). "To determine the role of CD44 in lymphovascular and MFP invasion present in Rb knockdown tumors, we implanted MCF7ras cells with stable single and double Rb/CD44 knockdowns into mouse MFPs and analyzed the effect of CD44 inactivation on primary tumor growth and metastatic progression." (PMID 24324613, 2013). "Because all of the 100 CD44+CD24low+ MDA-MB-231 cell injections yielded tumours, the L-Calc software could not be used to calculate T-ISC frequency." (PMID 23982961, 2013). "However, MT1-MMP and CD44 failed to co-localize at the cell surface of tumor cells undergoing transendothelial migration (not shown)." (PMID 24194929, 2013). "Hence, differences in tumour formation are not due to the variations in the expression of CD44 or EpCAM." (PMID 23150174, 2013). "It is thus evident from the results that the EMT-phenotype tumor cell growth and metastasis were significantly inhibited in the mice injected with the shZEB1 CD44+CD117+CSCs compared with the mice injected with the CD44+CD117+CSCs or the scrambled CD44+CD117+CSCs." (PMID 23842108, 2013). "There are reports that gastric TICs can be identified using the cell surface marker CD44 and that they form floating spheres in culture, but we could not obtain consistent results with our patient-derived tumor xenograft (PDTX) cells." (PMID 24015244, 2013). "Moreover, the tumors formed by CD44+CD24−/low Lin− cells could be serial passaged (self-renew) and also reproduce the tumor cellular heterogeneity observed in the initial tumor (differentiation)." (PMID 23986719, 2013).
tumor (continued). "The high level of CD44 expression by CSCs has been highlighted as one possible contributor, as both hyaluronan and osteopontin (OPN), common ligands for CD44, are expressed in the bone and other common sites of metastasis, suggesting a possible adhesive interaction for circulating tumor cell arrest." (PMID 22295241, 2012). "On tumor-infiltrating CTLs the expression of CD44 and CD45RB was comparable; no consistent and significant differences in their expression levels could be detected." (PMID 22808277, 2012). "In contrast, none of the mice inoculated with CD44/Sca1- cells developed tumor." (PMID 22277639, 2012). "Moreover, even in models where the proportion of CD133+ or CD44+ cells is enriched, the TRICs do not have an enhanced tumor initiating capacity." (PMID 23115623, 2012). "The difference in the relative frequency of CD44+/CD24- and ALDH1+ cells between basal-like and HER2+ tumor subtypes may reflect their distinct cell-of-origin or the alteration of stem cell-like gene expression programs due to tumor subtype-specific transforming events." (PMID 22452810, 2012). "However, no data is available concerning the pattern of CD44 isoforms and its modulation during tumour progression." (PMID 23151220, 2012). "Furthermore, combining CD44- or CD147-KD with DTX could have advantages over a single treatment approach and can greatly reduce tumor growth and reduce tumor burden." (PMID 22870202, 2012). "Similarly, 68% of CD44+CD24-/low positive tumours were node negative, compared to 60% of CD44+CD24-/low negative cases (P = 0.008)." (PMID 22112299, 2011). "ALDH1 status did not correlate with presence of CD44+/CD24- tumor cells." (PMID 21957977, 2011). "Also, the group of patients showing pCR had a higher proportion of CD44+/CD24− tumour cells than those not showing pCR, although the difference was not statistically significant." (PMID 21559013, 2011). "Given the striking association between the ability of fibroblasts to secrete PGE2 in vitro and the ability to expand CD44+/CD24−/EpCAM+ cells and support tumor growth, we speculated that perhaps PGE2 signaling enhances the tumor promoting phenotypes of fibroblasts." (PMID 21957456, 2011). "However, as observed in ER+ disease, CD44+CD24-/low positive tumours were more often node-negative in ER- cases also, with 64% of CD44+CD24-/low positive tumours being node-negative compared to 51% of CD44+CD24-/low negative cases (P = 0.012)." (PMID 22112299, 2011). "Clarke's group used similar xenograft techniques to show that CD44+/CD166+/EpCAMHigh cells isolated from human CRC could also establish a phenocopied tumor while no growth was observed with CD44-/CD166-/EpCAM Low cells." (PMID 21318087, 2011). "The overall CD44 expression level, however, was not up-regulated in tumor." (PMID 22168923, 2011). "CD44+/CD24− tumour cell proportion was not a significant predictive factor of pCR." (PMID 21559013, 2011). "In addition, we demonstrated that CD44 blocking antibody could block MMP-2 and MMP-9 secretion as well as tumor invasion in MCF-7/CD44st cells." (PMID 21749678, 2011). "Further support for this idea has lately been generated by the ability to isolate and assess the tumour-initiating properties of various cell fractions isolated by fluorescence-activated cell sorting (FACS) based on certain cell surface markers such as CD34, CD44 or CD133." (PMID 20426848, 2010). "Taken together, our present study suggests a negative role of PCBP1 in CD44 variants splicing and cell invasion in HepG2 cells, which raises the possibility that down-regulation of PCBP1 might be a biomarker in tumor metastasis." (PMID 20361869, 2010). "Interestingly, tumor cells were mostly positive for either CD44 or CD24 and rather few tumors contained double-positive cells, although it was quite common that individual tumors contained both CD44+ and CD24+ cells." (PMID 18559090, 2008).
tumor (continued). "Moreover, tumours from mice injected with CD44+CD24− cells phenotypically resembled tumours removed from mice injected with total LNCaP cells, indicating that CD44+CD24− cells can give rise to the heterogeneous population present in tumours derived from the LNCaP cell line." (PMID 18268494, 2008). "However, the mechanisms by which CD44 modulates the tumor cell transendothelial migration process are not fully understood." (PMID 18350162, 2008). "Additionally, given that the proportion of CSCs in untreated tumours could vary greatly between smokers and non-smokers, and correlate with poor prognosis, we assayed for CD44 and ALDH1 co-expression prior to radiation therapy." (PMID 40282522, 2025). "Notably, the ability of S1, S5, and S6 for Siglec-15 to disrupt interactions with key ligands (CD44, MAG, sialyl-Tn, and LRR4C) suggests a dual mechanism of action: direct blockade of Siglec-15-mediated immunosuppressive signaling and potential modulation of ligand-dependent tumor-stroma crosstalk." (PMID 40507880, 2025). "Additionally, CD44 is known to be a cell surface biomarker of cancer stem-like cells (CSLCs), and tumour cells with CSLC properties have high proliferative activity, clonogenic activity, tumour growth, and decreased apoptosis, and are able to survive chemotherapy." (PMID 38391955, 2024). "However, its implication in CD44-mediated tumor targeting via nanomedicine has never been studied." (PMID 38177179, 2024). "However, interactions involving TAMs signalling to malignant cells expressing CD44 via SPP1 and MIF, known to suppress T‐cell activation and promote TAM secretion of growth factors respectively, decreased after therapy, suggesting a transformation towards an anti‐tumour microenvironment." (PMID 39415331, 2024). "Furthermore, in a post-radiation tumor recurrence model, only 25% of mice exhibited recurrent tumor growth when treated with H4C4, compared to 90% of mice treated with radiation alone, indicating that the CD44+ tumor initiating population had been eradicated by H4C4 treatment." (PMID 38612911, 2024). "Interestingly, CD44, the receptor for hyaluronan, did not correlate with MRE stiffness, suggesting that stiff tumor cells may downregulate CD44 over time, losing their ability to monitor hyaluronan deposition." (PMID 38914647, 2024). "Interestingly, CD44 kd tumors showed nearly abolished CEACAM5 immunoreactivity in the paranecrotic areas (again, the area where CD44 was expressed in control tumors) compared to control tumors (P < 0.0001, unpaired t‐test), but not at the tumor margin (P = 0.6)." (PMID 37849446, 2024). "In addition, CD44+ CD8 T cells have been shown to mediate anti-tumour responses without inducing GVHD, suggesting that downregulation in GGF patients may diminish graft vs. tumour responses." (PMID 37818364, 2023). "Thus, our results suggest that deletion of Nf2 may specifically release tumor-promoting mechanisms that are independent of CD44; or alternatively, CD44 function is compensated by other molecules in Cd44-deficient Nf2-mutant mice." (PMID 37174657, 2023). "Thus, tumor spheres derived from OSCC cells exhibit increased stemness features along with elevated levels of pluripotent transcription factors and stem cell markers such as Lin28, NANOG, KLF4, OCT4, SOX2, CD44, and ALDH1 respectively in comparison to their attached monolayer counterparts." (PMID 38170015, 2023). "Similarly, the number of Tc17 cells (RORγt+ in CD8+), and activated and proliferating Tc17 (RORγt+Ki67+CD44+ in CD8+), which are emerging as an important pro-inflammatory cell types that induce cancer cell death, were also >10-fold significantly higher than the controls in the tumours." (PMID 37660049, 2023).